BRCA1 (BRCA1 DNA repair associated)
Diseases named in the same sentence as BRCA1 in open-access papers (continued):
Sharing a sentence is not in itself a finding about the gene and the disease.
breast cancer (continued). "The mutation prevalence of BRCA1 is generally low, being approximately only 7% in patients with non-familial breast cancer or ovarian cancer." (PMID 39125994, 2024). "The higher sensitivity of BRCA1 carriers to iodine may be age-related, as the average age of breast cancer diagnosis is 45 years when there is high estradiol activity." (PMID 38892720, 2024). "For BRCA1/2 mutation carriers, Huber examined OC users’ risk of ovarian cancer and breast cancer compared to non-users in a systematic review." (PMID 39606555, 2024). "However, the expression of both genes was greater in the breast cancer patients (p = 0.033 for BRCA1 and 0.049 for MGMT)." (PMID 38542081, 2024). "Nevertheless, when analyzed separately, there was a decrease in both high-grade serous cancer and breast cancer mortalities in BRCA1 mutation carriers, but not in BRCA2 mutation carriers." (PMID 38717180, 2024). "Roughly 10% of breast cancers result from inherited PVs in the BRCA1 and BRCA2 genes, most of which can be inherited in an autosomal dominant fashion as part of the Hereditary Breast and Ovarian Cancer (HBOC) syndrome and greatly increase the risk of developing breast cancer." (PMID 39682099, 2024). "PVs in BRCA1, BRCA2, CHEK2, and ATM increase the lifetime cancer risk of breast cancer." (PMID 38929805, 2024). "Additionally, 13 polymorphisms (4 in BRCA1 and 9 in BRCA2) were identified, of which 2 are associated with a moderate increase in breast cancer risk (BRCA2 c.1114A>C and c.875566T>C)." (PMID 39338246, 2024). "Mutations in BRCA1 and BRCA2 make up around 15% of female breast cancer (FBC)." (PMID 38275884, 2024). "The effect of high expression of ANXA1 in BC is highly connected with the type of BC present; however, in invasive basal-like breast cancer, triple negative breast cancer, familial breast cancer with BRCA1, and BRCA 2 high levels of ANXA1 were connected with poorer prognosis." (PMID 38892394, 2024). "Breast cancer patients were not different from BRCA1- (p = 0.405) or BRCA2- (p = 0.191) mutated patients." (PMID 37623237, 2023). "The majority of tumors in BRCA1 mutation carriers are of the triple-negative subtype while over 70% of tumors among BRCA2 carriers are luminal-like, a similar proportion as in the general population of breast cancer patients." (PMID 38036573, 2023). "Oncogene BRCA1-IRIS, tied to breast cancer, arises from differential BRCA1 locus utilization." (PMID 37746260, 2023). "Exploratory analyses of high-dose alkylating chemotherapy trials have suggested that BRCA1 or BRCA2-pathway altered (BRCA-altered) breast cancer might be particularly sensitive to this type of treatment." (PMID 37689749, 2023). "For example, advanced breast cancer patients with a germline BRCA1 or BRCA2 PV have a greater benefit to PARP inhibition than individuals with a somatic BRCA1 or BRCA2 PV, and the FDA-approval for PARP inhibition is currently confined to those with a germline PV4." (PMID 37833309, 2023). "Furthermore, having a family member with breast cancer can increase the chance of developing prostate cancer due to their genetic makeup (e.g., BRCA1, BRCA2, HOXB13, CHEK2, HOXB13 and ATM)." (PMID 37893854, 2023). "Thus, understanding these nuances in the relationship between BRCA1 and ER-negative BC necessitates further research focused on the molecular subtypes of breast cancer." (PMID 38201529, 2023). "We observed that BRCA1/2 testing is almost universally covered for those with a personal or family history in a first-degree relative (eg personal cancer diagnosed before age 50, family history of breast cancer, recurrent cancer, or those with ovarian cancer)." (PMID 37435610, 2023).
breast cancer (continued). "Its frequent epigenetic inactivation may facilitate the transformation of Her2+/BRCA1− mediated breast cancer by suppressing senescence." (PMID 37627161, 2023). "Most breast cancers arising in BRCA1 PV carriers belong to the triple-negative subclass." (PMID 38053165, 2023). "Molecular tests such as phosphoinositide 3-kinase mutations, breast cancer susceptibility gene 1 or 2 mutations (BRCA1 OR BRCA2) and PD-L1 expression were not done and the relevant targeted therapy was not given." (PMID 37396100, 2023). "BRCA1 and BRCA2 mutations, for instance, are linked to increased risks of endometrial and colorectal cancers, while Lynch syndrome is associated with a higher breast cancer risk." (PMID 38136308, 2023). "Therefore, it is important to understand the function of BRCA1 and BRCA2 (in DNA damage response) to appreciate why germline BRCA mutated breast cancers are susceptible to PARP inhibition." (PMID 35976445, 2023). "Nowadays, numerous phase III clinical trials have shown that various PARP inhibitors can improve treatment outcomes in both early and advanced germline BRCA1/2 (gBRCA1/2)-mutant breast cancer, as well as achieve a better quality of life, opposed to cytotoxic chemotherapy." (PMID 38098088, 2023). "Through meticulous analysis of BRCA1 animal models, coupled with probing investigations into altered chemotherapeutic sensitivity and hormone competition, we move closer to unraveling the intricacies of breast cancer’s development and progression." (PMID 37762577, 2023). "Familial breast cancer is in most cases unexplained due to the lack of identifiable pathogenic variants in the BRCA1 and BRCA2 genes." (PMID 37316882, 2023). "This investigation showcased BRCA1’s role in the regulation of cancer stem cell (CSC)-like traits by demonstrating that reintroducing BRCA1 led to a significant decline in CSC-like populations within breast cancer cells." (PMID 37762577, 2023). "Occurrence mutations in the BRCA1 and BRCA2 genes in the Czech Republic can be estimated at 2.8% based on the occurrence of population-specific variants in an unselected population of women with breast cancer." (PMID 37372873, 2023). "Notably, even fewer studies have characterised HER2, variably determined by either FISH or immunohistochemistry within non-BRCA1/2 (so-called BRCAX) familial breast cancers, with nine small studies showing a wide range of HER2 positivity (9–60%)." (PMID 36831687, 2023). "The triple-negative (TN) subtype is common in BRCA1 breast cancer." (PMID 36905492, 2023). "Recently published studies assessing the clinical validity of genes frequently tested in hereditary breast and ovarian cancer mostly agree that ATM, BRCA1, BRCA2, CHEK2, and PALB2 are strongly associated with a risk of breast cancer (overall with a p value of less than 0.0001)." (PMID 37239898, 2023). "BRCA1 and BRCA2 mutations contribute to both breast cancer and ovarian cancer worldwide." (PMID 37312208, 2023). "In this study, we used the latest genetic sequencing technologies to investigate hereditary causes for the second breast cancer in individuals who are known not to have alterations in one of the three main breast cancer genes (BRCA1, BRCA2 and PALB2)." (PMID 36672364, 2023). "Breast cancer gene-1 (BRCA-1) can be quickly and effectively identified with this approach." (PMID 36832253, 2023). "There is reassuring data on the use of short-term HRT in BRCA1\2 mutation carriers without a personal history of breast cancer after prophylactic bilateral salpingo-oophorectomy." (PMID 36614207, 2023).
breast cancer (continued). "Due to the proximity of the MS locus to the BRCA1 gene, this condition may lead to breast cancer and MS simultaneously." (PMID 38031938, 2023). "Unaffected women with familial breast cancer were about 2-times more likely to carry a PV in one of the high-penetrance breast cancer-risk genes (BRCA1, BRCA2, PALB2) compared to those with no familial breast cancer." (PMID 37084156, 2023). "These authors reported the lowest prevalence of this variant in patients negative for BRCA mutations compared to BRCA1 mutated and sporadic breast cancer patients." (PMID 36758048, 2023). "BC occurs mainly due to somatic, genetic, and epigenetic alterations in a lifetime (i.e., non-hereditary), while only 5%–10% of BC cases are hereditary [majority detected with mutations in two tumor-suppressor genes: breast cancer gene 1 (BRCA1) and breast cancer gene 2 (BRCA2)]." (PMID 38090567, 2023). "If these findings are assessed carefully, we could avoid the misidentification of BRCA1 breast cancers." (PMID 36905492, 2023). "To address the question of whether the resistance is correlated with BRCA1 mutation, we knocked down ZNF251 in an isogenic BRCA1-wildtype and -mutated HCC1937 human breast cancer cell lines." (PMID 37066268, 2023). "In addition to the BRCA1 and BRCA2 genes, there are several other genes associated with an increased risk of breast cancer." (PMID 37958392, 2023). "al. shown that arsenic is one of risk factors for breast cancer for carriers and non-carrier of deleterious variants in BRCA1 gene." (PMID 37434214, 2023). "We propose that all women of Orcadian ancestry (worldwide) with a diagnosis of breast cancer should be offered a targeted test for this variant, if a BRCA1/BRCA2 gene screen is not offered as part of their clinical care." (PMID 36927983, 2023). "We assessed the PREDICT v 2.2 for prognosis of breast cancer patients with pathogenic germline BRCA1 and BRCA2 variants, using follow-up data from 5453 BRCA1/2 carriers from the Consortium of Investigators of Modifiers of BRCA1/2 (CIMBA) and the Breast Cancer Association Consortium (BCAC)." (PMID 37173335, 2023). "Previous articles have also recommended that randomized controlled trials be conducted to assess the surgical safety, patient reported outcomes (PROs), and oncologic outcomes of RNSM and thus evaluate its clinical role in treating BRCA1/2 carriers and patients with breast cancer." (PMID 37344780, 2023). "Of the 19 persons with cancer carrying BRCA2 variants, eight had breast cancer, seven of which lacked BRCA1 variants." (PMID 37306523, 2023). "Our findings suggest prenatal BRCA1 epimutations might be the underlying cause of around 20% of TNBC and low-ER expression breast cancers." (PMID 38053165, 2023). "Inherited mutations in BRCA1 and BRCA2 account for a small percentage of breast cancer cases." (PMID 37627192, 2023). "BRCA1 breast cancers tended to be posteriorly accentuating and hypervascular." (PMID 36905492, 2023). "Overall, authors concluded that ET after oophorectomy in BRCA1 carriers does not increase the risk of breast cancer: however, the possible adverse effect of EPT use in this population requires further investigation." (PMID 36765666, 2023). "Additionally, genetic factors also played a key role in the growing incidence of breast cancer in the SACU region, and it’s confirmed the variants in the two major genes, BRCA1 and BRCA2, and in five other genes in the patients in South Africa." (PMID 36761973, 2023). "Additionally, radiotherapy and platinum-based chemotherapy need personalized application in breast cancer patients with BRCA1/2 (Peleg Hasson, Menes & Sonnenblick, 2020)." (PMID 37426414, 2023). "Since BRCA1 is important for deoxyribonucleic acid (DNA) double-strand break repair, the upregulation of cathepsin O contributes to the neoplastic transformation of breast cancer cells." (PMID 36002710, 2023).
breast cancer (continued). "Risk-reducing salpingo-oophorectomy (RRSO) reduces the relative risk of ovarian cancer by about 80% and breast cancer by about 40% in woman with BRCA1/2 mutations who had no history of breast cancer." (PMID 36849964, 2023). "In the subset of IBR, 52 procedures (50.5% of reconstructive surgeries) were performed in 48 women (82.8% of the operant group) with non-advanced breast cancer or BRCA1/2 mutation." (PMID 37372873, 2023). "Finally, we examined the correlation of TRIM47 and BRCA1 in collected clinical breast cancer samples." (PMID 36906594, 2023). "Furthermore, results demonstrate a substantial link between lower levels of BRCA1 protein and the overexpression of miR-155-5p in BRCA1 mutant human breast cancers." (PMID 37240365, 2023). "The estimated lifetime risk of acquiring breast cancer with an ATM, CHEK2, PALB2 mutation is greater than 20% which is considered a “moderate risk” compared to the effects of the pathogenic variants in BRCA1 and BRCA2 genes with a lifetime risk of approximately 50%." (PMID 37239898, 2023). "Additionally, a total of 16 gene records were retrieved for breast cancer, which includes but is not limited to BRCA1, RB1, APC and PTEN." (PMID 37195695, 2023). "BRCA1 and BRCA2 gene mutations are the most well-known genetic changes linked to breast cancer." (PMID 37886170, 2023). "A small pilot study of such a protocol in BRCA1 gene mutation carriers found a substantial decrease in mammographic density (breast cancer risk surrogate) with no adverse effects on quality of life or bone mineral density." (PMID 36835955, 2023). "Conversely, short-term treatment before the age of natural menopause does not appear to increase the cancer risk in BRCA1 mutation carriers without a personal history of breast cancer after prophylactic surgery." (PMID 36614207, 2023). "Three SNPs in this region were positively associated with breast cancer; they were not in LD with BRCA1, which is also located in this region." (PMID 36788297, 2023). "This trial determined that olaparib could be used as maintenance therapy for early breast cancer patients who are HER2-negative and have BRCA1/2 germline mutations." (PMID 37035242, 2023). "Of the 40 women, 18 (45%) had no known mutation in breast cancer genes, 20 of 40 (50%) had a pathologic variant of BRCA1/2, and 2 of 40 (5.0%) had a pathologic variant of other breast cancer genes." (PMID 34851154, 2023). "Previously, we have identified pathogenic mutations of BRCA1, BRCA2, CHEK2, and PALB2 in about half of 1018 Polish families with hereditary breast cancer, and we have observed that 18 founder mutations are responsible for about 80% of all the mutations detected in these genes." (PMID 37510234, 2023). "Data pertaining to the risk of seizures among women with advanced or metastatic breast cancer is limited, particularly when considering women who may harbor a mutation in the high risk BRCA1 and BRCA2 breast cancer predisposition genes." (PMID 36690978, 2023). "HRT use among RRSO patients did not significantly alter postsurgical breast cancer risk (HR 1.35; 95% CI, 0.16 to 11.58), including in BRCA1 mutation carriers." (PMID 36614207, 2023). "If a BRCA1 or BRCA2 mutation is present, affected individuals develop breast cancer about 20 years earlier than women with sporadic cancer, with a cumulative lifetime risk of 60% on average for developing breast cancer and 16–55% for developing ovarian cancer." (PMID 36765786, 2023). "Despite not being included in first-line regimens for breast cancer, cisplatin and gemcitabine show therapeutic effectiveness in BRCA1-deficient MMECs." (PMID 37513983, 2023). "A single-center study of 488 breast cancer patients found a BRCA1/2 pathogenetic variant in 6.1% of women (5.1% in non-Ashkenazi Jewish patients)." (PMID 37958491, 2023).
breast cancer (continued). "Therefore, the future research direction would focus on conducting clinical trials of PARPi, including efficacy, safety, and combination therapy in the different subtypes of BRCA1/2-mutant breast cancer." (PMID 37476378, 2023). "PGZ-activated PPARγ targets estrogen receptors (ER) and aromatase, activates the tumor suppressor gene PTEN to inhibit ER expression or induce proteasome-dependent ER degradation, and inhibits aromatase through PGE2 and BRCA1 signaling pathways to prevent breast cancer progression." (PMID 37251321, 2023). "The same study found that among women aged <35 years diagnosed with breast cancer and no family history, 9.4% (7.1% for BRCA1 and 4.9% for BRCA2) were carriers of germline mutations." (PMID 36980802, 2023). "Tamoxifen did not decrease breast cancer incidence among healthy patients with BRCA1 germline variants." (PMID 37628558, 2023). "Therefore, next, the non-oncologic BRCA1/2 were compared with the healthy female individuals and the oncologic BRCA1/2 were compared with the patients with breast cancer." (PMID 37623237, 2023). "Germline mutations in BRCA1 and BRCA2 genes not only increase the risk of breast and ovarian cancer, but also contribute to the susceptibility of pancreatic and prostate cancer." (PMID 38274092, 2023). "However, the most common and well-known examples are the pathogenic BRCA1 and BRCA2 genomic variants, present in 1 to 300–500 women and responsible for 5–10% of breast cancers, and 10–15% of ovarian cancers." (PMID 36826146, 2023). "One of the two patients with BRCA1*c.3143delG also had breast cancer." (PMID 37013556, 2023). "In addition to BRCA1 and BCRA2 genes, other genes, such as CHEK2, PALB2, and PTEN, are less common but also confer an elevated risk of breast cancer among men." (PMID 38146568, 2023). "BPBC patients with a family history of breast cancer had a higher risk of germline BRCA1/2 mutations than those patients without a family history." (PMID 37293877, 2023). "Moreover, the risks of esophageal cancer and lymphoma were markedly elevated in male relatives of BRCA1 carriers, and the risks of esophageal, kidney, and breast cancers in male relatives of BRCA2 carriers were also increased." (PMID 36861435, 2023). "This hesitation may be heightened among BRCA1 and BRCA2 mutation carriers due to their differing baseline risks of breast cancer." (PMID 36765666, 2023). "BRCA1 has received great attention in breast cancer but little research in gliomas." (PMID 37759912, 2023). "Two studies were conducted using familial breast cancer cases with no BRCA1 or BRCA2 pathogenic variants and controls from the general population." (PMID 36707629, 2023). "BRCA1/2 mutation of patients undergoing NSM and BCS for breast cancer in the Xiangya cohort." (PMID 38053723, 2023). "In addition, the methylation of homologous recombination gene promoters such as BRCA1 and RAD51C lead to homologous recombination-deficient breast cancer development in sporadic cases." (PMID 37504297, 2023). "Most BRCA1-associated breast cancers are invasive ductal carcinomas of non-special type and fall into the “basal-like” intrinsic molecular subtype." (PMID 37239058, 2023). "Early termination also precluded further stratification by BRCA1/2mut and breast cancer subtypes." (PMID 37803017, 2023). "Nevertheless, about 30% of the breast cancer patients who have a family history of inherited breast cancer do not carry BRCA1/2 variants." (PMID 37656691, 2023). "For high-risk individuals with BRCA1 or BRCA2 mutations considering combined OCPs, genetics consultation should be considered to judge the competing impacts of increased breast cancer risk against individual needs and potential protective effects against ovarian cancer." (PMID 36980802, 2023). "The difference in the association between BRCA1 and BRCA2 carriers may be explained by the difference in proportions of estrogen receptor (ER)-positive breast cancer (22% for BRCA1, 77% for BRCA2)." (PMID 37340476, 2023).